CSF1 (colony stimulating factor 1)
Diseases named in the same sentence as CSF1 in open-access papers (continued):
Sharing a sentence is not in itself a finding about the gene and the disease.
breast cancer (continued). "Our results confirmed that the decreased CSF-1R expression is accompanied by the lower ability of cancer cells to invade matrix, whereas the presence of CSF-1 in the culture medium increased canine mammary cancer cells invasion in Matrigel matrix." (PMID 23561040, 2013). "It has been shown previously that in breast cancer cell lines administration of CSF-1 activates cyclin D1, as a consequence of ERK1/2 activation." (PMID 23561040, 2013). "We have assessed the impact of csf-1r knockdown and CSF-1 supplementation on growth characteristics of canine mammary cancer cells on Matrigel matrix." (PMID 23561040, 2013). "By combining the stromal signatures of EF and FOTS, with our previously identified DTF and TGCT/CSF1 signatures we can now characterize clinically relevant stromal expression profiles in the TME for between 74% to 90% of all breast cancers." (PMID 24342436, 2013). "Direct evidence of the role of TAMs in tumorigenesis is observed in breast cancer mouse models in which colony-stimulating factor-1 (CSF-1)-dependent TAM recruitment is required for tumor initiation through the stimulation of tumor angiogenesis." (PMID 23372702, 2013). "In the MMTV-PyMT (PyMT) mouse model of spontaneous breast cancer, CSF-1 produced by tumor cells was indeed shown to be an important chemoattractant for macrophages and to enhance their infiltration into the primary tumor." (PMID 24019914, 2013). "FOTS+/TGCT/CSF1+ breast cancers account for 6 to 12% of the cases, whereas FOTS-/TGCT/CSF1- breast cancers account for 41 to 65% of the cases in the four breast cancer datasets." (PMID 24342436, 2013). "FOTS-/TGCT/CSF1- breast cancers demonstrated significantly better outcome in overall survival, disease specific survival and disease free survival." (PMID 24342436, 2013). "In order to test the prognosis power of the combined core gene sets of EF, FOTS, DTF and TGCT/CSF1, we pooled the outcome data from four breast cancer datasets in overall survival (OS), disease specific survival (DSS) and disease free survival (DFS)." (PMID 24342436, 2013). "Taken together with the two previously identified stromal signatures (DTF and TGCT/CSF1 signatures), the combined four stromal signatures now classify 74% to 90% of breast carcinomas." (PMID 24342436, 2013). "CSF-1 protected osteoclasts from suppressive effects of transforming growth factor beta (TGF-beta) in a mouse mammary tumor cell line." (PMID 22554285, 2012). "In contrast, expression of the macrophage colony stimulating factor-1 (CSF-1) response pathway, previously identified as a poor prognostic marker in breast cancer, predicted poor outcome in the group III subclass of LMS." (PMID 22448121, 2012). "Further, IM was able to prevent in part the activation of ERK1/2 induced by CSF-1 confirming the involvement of ERK1/2 in the proliferative effect of CSF-1 in breast cancer cells." (PMID 22096574, 2011). "The wide expression of the CSF-1/CSF-1R pair across breast cancer cell subtypes supports CSF-1/CSF-1R targeting in breast cancer therapy." (PMID 22096574, 2011). "The wide expression of CSF-1/CSF-1R pair across breast cancer cell subtypes supports CSF-1/CSF-1R targeting in breast cancer therapy." (PMID 22096574, 2011). "In the present study we found that: i) breast cancer cell lines consistently express CSF-1 and CSF-1R; ii) the CSF-1/CSF-1R pair sustains the proliferation of breast cancer cell lines; iii) ERK1/2 is downstream CSF-1R in proliferating breast cancer cells." (PMID 22096574, 2011). "Consistent with this, in breast cancer patients, the expression of both CSF-1 and its receptor in neoplastic epithelial cells strongly correlates with poor prognosis and is predictive of ipsilateral recurrence." (PMID 22096574, 2011).
breast cancer (continued). "In mouse models of invasive breast cancer, macrophage-secreted epidermal growth factor (EGF) stimulates growth and migration of mammary tumor cells, which in turn secrete colony stimulating factor-1 (CSF-1) to recruit additional macrophages to the tumor site." (PMID 21699731, 2011). "The role of CSF-1/CSF-1R in the proliferation of breast cancer cells was then studied in MDAMB468 and SKBR3 cells belonging to different subtypes." (PMID 22096574, 2011). "Our data are in line with previous studies in which breast cancer cell lines expressing ectopic CSF-1R showed increased expression of cyclin D1 as a consequence of ERK1/2 activation upon CSF-1 administration." (PMID 22096574, 2011). "The relevance of ERK1/2 in CSF-1R signaling was highlighted by the fact that enhancement of ERK1/2 phosphorylation upon CSF-1 treatment was found in 10 out of 17 breast cancer cell lines." (PMID 22096574, 2011). "In this respect, it is to note, however, that both ERK5 and PI3K pathways are often constitutively active in breast cancer cells, possibly masking a response to CSF-1." (PMID 22096574, 2011). "When 10 μM IM was given to SKBR3 and MDAMB468 breast cancer cell lines for 48 hours in the presence of CSF-1, cell number was markedly reduced, as determined by crystal violet staining." (PMID 22096574, 2011). "The expression of CSF-1R and/or CSF-1 strongly correlates with poor prognosis in several human epithelial tumors, including breast carcinomas." (PMID 22096574, 2011). "The expression of CSF-1R and/or CSF-1 in human breast carcinomas has been documented in both cell lines and tumors samples." (PMID 22096574, 2011). "Previous reports implicate CSF-1 secreted by breast cancer cells as the exclusive chemoattractant for TAMs." (PMID 19696929, 2009). "This work is in agreement with previous studies that have shown that CSF-1 secretion by breast cancer cells is a potent chemoattractant for macrophages in vitro and in vivo." (PMID 19696929, 2009). "Therapeutic strategies targeting TAMs in breast cancer have evolved from depletion approaches (CSF1/CSF1R blockade) to inhibition of monocyte recruitment (CCL2/CCR2 axis), functional reprogramming (CD40 agonism, PI3Kγ inhibition), and macrophage-directed checkpoint modulation (CD47-SIRPα axis)." (PMID 42122206, 2026). "Paclitaxel treatment induced the expression of colony-stimulating factor (CSF)-1 in tissues from chemoresistant breast cancer xenografts, which stimulated the recruitment of TAMs, while CSF-1 signaling inhibition reduced TAM recruitment and restored paclitaxel antitumoral effects." (PMID 39863855, 2025). "Furthermore, EGF produced by TAMs in tumor tissues activates EGF receptors expressed on breast cancer cells, establishing a positive feedback loop between cancer cells and TAMs through CSF-1/EGF signaling." (PMID 40940867, 2025). "Furthermore, the demethylation of m 1A by ALKBH3 increases the stability of colony stimulating factor-1 (CSF-1) mRNA, promoting the invasion of breast cancer and ovarian cancer cells." (PMID 40483535, 2025). "Additional studies have evaluated CSF-1 inhibitors in breast cancer." (PMID 39625569, 2025). "Moreover, deletion of CSF-1 leads to reduced breast cancer incidence, slower tumor progression, and decreased metastasis." (PMID 39003350, 2024). "Additionally, ALKBH3 has been found to improve the translation efficiency by demethylating m1A on CSF‐1 (colony stimulating factor 1) mRNA, enhancing the aggressiveness of ovarian and breast cancer cells." (PMID 39175405, 2024). "Indeed, a correlation between increased circulating CSF-1 and enhanced CSF-1R+ TAMs was observed in breast cancer." (PMID 38254773, 2024). "In mouse models of breast cancer, CSF1 signaling in TAMs has been demonstrated to enhance the invasiveness and infiltration of breast cancer cells in vivo, and inhibiting this signaling can suppress tumor growth by reducing TAM numbers and increasing CD8+ T-cell infiltration." (PMID 39769140, 2024).
breast cancer (continued). "Hence, blockade of colony-stimulating factor-1 (CSF-1) limits macrophage infiltration and improves response of mammary carcinomas to chemotherapy." (PMID 37173915, 2023). "Macrophages may also favor carcinoma cell invasion through a CSF-1/epidermal growth factor paracrine loop, as described in breast cancer." (PMID 36555673, 2022). "Finally, we extend our findings beyond breast cancer by demonstrating that enhancer transcription and eRNA transcripts are necessary for CSF1 enhancer function in ovarian cancer." (PMID 35406623, 2022). "Intriguingly, nucleolin binds to CSF-1 mRNA to promote its translation in breast cancer cells." (PMID 36359210, 2022). "Interestingly, deletion of CSF-1 not only reduced the incidence of breast cancer and delayed tumor progression but also decreased metastasis." (PMID 34207035, 2021). "In a mouse model bearing chemoresistant MCF-7 breast cancer cells, injection of a murinized antigen-binding fragment targeting mouse CSF-1 retards tumor growth, enhances response to chemotherapeutic agents—including cyclophosphamide, methotrexate, and 5-FU—and prolongs survival of the mice." (PMID 34359674, 2021). "It is possible that CSF1 may function in concert with other players, which could also be secreted by breast cancer cells, to work together to stimulate CXCL7 expression robustly." (PMID 34789744, 2021). "Among them, CSF1 is crucial for the differentiation and survival of macrophages, and elevated expression of CSF1 correlates with high grade and poor prognosis in breast cancer." (PMID 34789744, 2021). "TAMs are recruited to TME by CSF-1 and promote breast cancer development and metastasis." (PMID 34359674, 2021). "The upregulation of CSF-1 signaling correlates with increased breast cancer progression." (PMID 33747948, 2021). "Colony-stimulating factor 1 (CSF-1), also known as macrophage colony-stimulating factor (M-CSF), and granulocyte-macrophage colony-stimulating factor (GM-CSF) are other tumor-derived factors produced by breast cancer cells." (PMID 33968034, 2021). "Notably, the transcripts of PEAK1-suppressed MSC factors (i.e., TGFB3, VEGFA and CSF1) were significantly lower within breast cancer stroma (left three graphs)." (PMID 34239043, 2021). "We found CSF1, which was secreted by breast cancer cells, could directly stimulate CXCL7 expression in monocytes." (PMID 34789744, 2021). "In addition, elevated serum CSF1 has been detected in patients with breast cancer and have been correlated with an adverse prognosis." (PMID 32801364, 2020). "Moreover, it has been noted that the enhanced expression of Csf1 was correlated with a worse prognosis of overall survival in breast cancer and with increased infiltration of TAMs in colorectal cancer." (PMID 32887237, 2020). "Additionally, macrophage depletion with either CSF-1 antibody or CSF-1 receptor kinase inhibitor (i.e. PLX3397) significantly reduces tumor regrowth followed by radiotherapy in mice bearing mammary tumor." (PMID 31629410, 2019). "CSF-1 can also colocalize with CSF-1R in the nucleus in breast cancer cells." (PMID 31565097, 2019). "The function of CSF1/CSF-1R remains controversial also in experimental models of breast cancer." (PMID 31406165, 2019). "Genetic deletion of CSF-1 resulted in reduction of mammary TAMs and in lower incidence of lung metastasis in in vivo mammary tumor mouse models, deletion of ETS2 in macrophages resulted in reduced metastatic tumor burden and its elevated expression has been correlated with human breast cancer." (PMID 31057539, 2019). "For instance, work in a spontaneous mammary tumor model showed that IL-4/IL-13-activated TAMs, when exposed to tumor-derived colony-stimulating factor-1 (CSF-1), produce epidermal growth factor (EGF), which in turn promotes motility and intravasation of EGF receptor (EGFR)-expressing tumor cells." (PMID 30355585, 2018).
breast cancer (continued). "However, while the role of CSF-1/CSF-1R has been extensively studied in breast cancer, the implication of IL-34 in breast cancer formation and progression is still poorly understood." (PMID 29796177, 2018). "To clarify the signaling basis by which IL-34 and M-CSF may differently regulate breast cancer cells, we investigated signaling events triggered by IL-34 and CSF-1." (PMID 29796177, 2018). "Despite the known expression of CSF-1 and CSF-1R in human breast cancer and their clear therapeutic potential, the role of IL-34 remains unclear." (PMID 29796177, 2018). "In a study using a mouse model for breast cancer it was demonstrated that CSF1 may promote metastatic potential by regulating the infiltration and function of TAMs." (PMID 28053982, 2016). "In breast cancer, TAMs have been shown to promote tumor invasion and metastasis by establishing a paracrine chemotactic loop whereby breast carcinoma cells secrete colony stimulating factor-1 (CSF-1) and TAMs secrete epidermal growth factor (EGF) to induce co-migration of both cell types." (PMID 31453214, 2016). "In fact, using a metastatic breast cancer model it was possible to comprehend that the paracrine loop signaling between TAMs, which supply EGF, and breast cancer cells, which on the other hand supply CSF1, is sufficient for the promotion of invasion and migration." (PMID 28053982, 2016). "Furthermore, breast cancer cells are not only a source of CSF-1 as already described, but also a source for IL-34, the alternative ligand for the CSF-1R." (PMID 26098772, 2015). "Moreover, analysis of lung and breast cancer brain metastasis revealed significant differences of CSF-1 and CSF-1R expression." (PMID 26098772, 2015). "Thus, we tested the gene expression of CSF-1 and CSF-1R in primary tumor samples and correlated their expression to the molecular breast cancer subtypes as well as the incidence of metastases." (PMID 26098772, 2015). "In line with the variable results of CSF1/CSF1R blockade, CSF1 gene signatures themselves were found to be either associated with poor survival or with improved survival, depending on the specific subtype of breast cancer." (PMID 26635798, 2015). "Additionally, we analyzed a subset of primary breast cancer patients, and certain patients with brain metastasis of lung and breast cancer and found high CSF-1R, CSF-1 and/or IL-34 expression, respectively." (PMID 26098772, 2015). "The expression of several extracellular matrix and collagen genes has been related to invasion and survival in other tumors, and studies in breast cancer described two types of stromal responses: a fibromatosis-like stromal gene signature and a CSF-1 macrophage stromal gene signature." (PMID 24950699, 2014). "In order to make these signatures more comparable and reproducible, we defined the DTF fibroblast breast cancers and TGCT/CSF1 macrophage breast cancers by the same criteria as the criteria for EF/FOTS-like cases (cases with high expression of signature and >0.2 correlation within clusters)." (PMID 24342436, 2013). "The fact that CSF-1 promotes proliferation in breast cancer cells prompted us to determine whether their growth is sensitive to tyrosine kinase inhibitors used in the clinic." (PMID 22096574, 2011). "Indeed, interfering with CSF-1/CSF-1R signaling, either by targeting the receptor or by blocking the ligand binding, impacts on breast cancer cell proliferation." (PMID 22096574, 2011). "To test whether an autocrine CSF-1/CSF-1R loop exists in breast cancer cells we used a CSF-1-blocking antiserum." (PMID 22096574, 2011). "We found that IM impairs the proliferation of breast cancer cell lines in the presence of CSF-1." (PMID 22096574, 2011). "However, the expression of CSF-1R and/or CSF-1 has been documented in several human cancers, including carcinomas of breast, female reproductive tract, prostate and kidney." (PMID 22096574, 2011).
breast cancer (continued). "Also, CSF-1/CSF-1R inhibitors, including kinase inhibitors and antibodies, can attenuate angiogenesis, metastasis, and proliferation of tumor cells and reprogram cancer cell growth in breast cancer models." (PMID 39003350, 2024). "Interestingly, Kindlin-2 has been reported to control the recruitment of immunosuppressive (F4/80+, CD206+) macrophages in orthotopic breast cancer models; Kindlin-2 in the tumor cells is required for the secretion of colony-stimulating factor-1 that acts as a chemoattractant for the macrophages." (PMID 36883731, 2023). "Interestingly, increased expression of RSAD2 is associated with worse survival for breast cancer patients, and to our knowledge, the relationship between CSF1 and RSAD2 has not been shown before." (PMID 35406623, 2022). "While HER2 is the most common target identified in breast cancer, other major targets include, adenosine receptor targets, nonspecific tumor-associated antigens (TAA), immune checkpoints (PD-1, PD-L1), toll-like receptors (TLRs), and colony-stimulating factor-1 (CSF1/R)." (PMID 36351947, 2022). "However, the induction of CXCL7 by recombinant CSF1 alone was only 2–6 folds compared with untreated control, which is much less than the hundred folds induction of the mRNA we observed in monocytes co-culturing with breast cancer cells." (PMID 34789744, 2021). "Moreover, in addition to promoting tumor cell extravasation via local release of VEGF-A, CCR2-expressing monocytes give rise to immune-suppressive MAM-precursors that exhibit resistance to CSF-1 blockade and promote pulmonary seeding of mammary carcinoma cells." (PMID 33924237, 2021). "Moreover, immune checkpoint blockade could be combined with agents (e.g., CSF-1 inhibitors) that can inhibit TAMs accumulation and/or re-programme macrophages towards a more anti-tumoral M1-like phenotype in selected breast cancer patients." (PMID 31581535, 2019). "identify a breast cancer tumor-associated macrophage (TAM) transcriptome that is different from those of monocytes and tissue-resident macrophages, and which is associated with shorter disease-specific survival, and they demonstrate crosstalk between tumor cells and TAMs via SIGLEC1, CCL8, and CSF1." (PMID 30930117, 2019). "CSF-1 is secreted by ductal epithelial cells to recruit macrophages, which are required for normal mammary gland development and homeostasis, but it is also secreted by breast cancer cells to recruit TAMs, which promote progression of the cancer to invasion and metastasis." (PMID 28629162, 2017). "Furthermore, HMECs secrete CSF-1 in high levels that could promote the proliferation of breast cancer cells." (PMID 28567162, 2017). "In addition, 6 to 12% of breast cancers were positive for both of FOTS and TGCT/CSF1 core gene sets, 41 to 65% of breast cancers were negative for both FOTS and TGCT/CSF1 core gene sets, 5 to 24% of breast cancers were FOTS+/TGCT/CSF1-, and 23 to 24% of breast cancers were FOTS-/TGCT/CSF1+." (PMID 24342436, 2013). "Although the expression of CSF-1/CSF-1R has been previously documented in breast cancer and shown to correlate with poor prognosis, few studies have been performed to understand the role of CSF-1R-dependent signaling in the proliferation of breast cancer cells or other solid tumors." (PMID 22096574, 2011). "Similarly, macrophages recruited to the tumour microenvironment through the production of colony stimulating factor-1 (csf-1) by breast carcinomas can themselves release growth factors such as egf that can enhance both the proliferation of and invasion by tumour cells." (PMID 22792017, 2006). "The aberrant activity of the Ras/MAPK pathway has been identified as pivotal in the initiation and progression of breast cancer, miR‐21's targeting of key activators within this pathway, including ABCB1, AR, CDK6, CSF1, EREG, MKDR, among others." (PMID 40567015, 2025).